NRP1 (neuropilin 1)
Diseases named in the same sentence as NRP1 in open-access papers (continued):
Sharing a sentence is not in itself a finding about the gene and the disease.
endometrial cancer (3 papers, 2016 to 2024). Primary or metastatic malignant neoplasm involving the endometrium (mucous membrane that lines the endometrial cavity). "Due to tumor functions associated with aberrant NRP-1 expression in various human malignancies, we began by screening endometrial cancer specimens for the expression of NRP-1 using Western blots of protein extracts from frozen specimens." (PMID 26701889, 2016). "Together, these data demonstrate robust NRP-1 expression in early-stage endometrial cancer, and shows positive associations of NRP-1 expression in tumors with circulating levels of various tumor-promoting cytokines." (PMID 26701889, 2016). "Our study aimed to determine whether IL-4, IL-7, IL-9, IL-10, NT, TSP-2, and NRP1 could be diagnostic markers for endometrial cancer in women." (PMID 39334861, 2024). "IL-4, IL-7, IL-9, NT, and NRP1 may be useful diagnostic markers for endometrial cancer." (PMID 39334861, 2024). "The initial study presented here demonstrates the clinical utility of IL-4, IL-7, IL-9, NT, and NRP1 in endometrial cancer." (PMID 39334861, 2024). "Given the scarcity of data on these proteins in endometrial cancer, this study aims to evaluate the diagnostic potential of preoperative serum concentrations of IL-4, IL-7, IL-9, IL-10, NT, TSP-2, and NRP1." (PMID 39334861, 2024). "This study suggests the clinical utility of IL-4, IL-7, IL-9, NT, and NRP1 in the diagnosis of endometrial cancer." (PMID 39334861, 2024). "Retrospective studies involving NRP-1 expression and further investigations within later-stage endometrial cancer patients are further warranted." (PMID 26701889, 2016). "The purpose of this study was to determine if IL-4, IL-7, IL-9, IL-10, NT, TSP-2, and NRP1 could be used as novel, helpful markers for the detection of endometrial cancer." (PMID 39334861, 2024). "Finally, we evaluated the significance of IL-4, IL-7, IL-9, IL-10, NT, TSP-2, and NRP1 in the diagnosis of endometrial cancer." (PMID 39334861, 2024). "In endometrial cancer specimens, loss of LKB1 expression inversely correlated with NRP-1 levels." (PMID 26701889, 2016). "Prominent NRP-1 roles in axonal guidance of developing nervous system is in agreement with reported metastatic property in malignant cells, however, the expression profile and potential contributions of NRP-1 to endometrial cancer metastases remain unknown." (PMID 26701889, 2016). "Majority of the specimens were from early stage cancer patients, indicating that aberrant NRP-1 expression may represent an early event in endometrial cancer." (PMID 26701889, 2016).
epilepsy (3 papers, 2021 to 2023). A brain disorder characterized by episodes of abnormally increased neuronal discharge resulting in transient episodes of sensory or motor neurological dysfunction, or psychic dysfunction. "Nrp1 is abundantly expressed in the neurons and plays an important role for axon guidance, regeneration, neuronal plasticity, or various human diseases, such as epilepsy and seizure." (PMID 34745215, 2021).
Granuloma (3 papers, 2020 to 2023). A compact, organized collection of mature mononuclear phagocytes, which may be but is not necessarily accompanied by accessory features such as necrosis. "A reverse correlation between IL6 and ACE2, NRP1 and TMPRSS2 gene expression in periapical abscesses and granuloma was noted." (PMID 35163355, 2022).
head and neck cancer (3 papers, 2012 to 2026). A primary or metastatic malignant neoplasm affecting the head and neck. "Because VEGF is often up-regulated in a majority of malignancies, including head neck cancer, SEMA3A signalling might be inhibited by the binding of VEGF to NRP1." (PMID 22926477, 2012). "However, the roles of SEMA3A and its receptor NRP1 have not been extensively studied, particularly in the long-term survival of patients with head and neck cancer." (PMID 22926477, 2012).
Hypoglycemia (3 papers, 2014 to 2023). A decreased concentration of glucose in the blood. "An elevation of sNRP1 levels in association with its proteolytic enzyme as well as ligands post-hypoglycemia suggests the possible connection of glycemic control with NRP1 cleavage in obese T2D subjects." (PMID 34248841, 2021). "However, 4-hours post-hypoglycemia, NRP1 was elevated in T2D (2476 ± 117 vs 2216 ± 94 RFU, T2D vs control, p=0.04)." (PMID 34248841, 2021). "We also showed hypoglycemia resulted in diminishing NRP-1 expression from EOC." (PMID 25401697, 2014). "Here we report the levels of soluble neuropilin-1 (sNRP1), NRP1 proteolytic enzyme ADAM9 and NRP1 ligands, VEGF and SEMA3A, in response to insulin-induced hypoglycemia in obese patients with T2D." (PMID 34248841, 2021). "Neuropilin-1 was highly expressed in all the cells and was more stable than VEGFR2 under hypoglycemia." (PMID 25401697, 2014).
Insulin resistance (3 papers, 2020 to 2022). Increased resistance towards insulin, that is, diminished effectiveness of insulin in reducing blood glucose levels. "In addition to M1 and M2 macrophages, other macrophage populations that regulate insulin resistance have been reported recently, including neuropilin-1 (NRP1)+ macrophages and TREM2+ lipid-associated macrophage (LAM)." (PMID 36119080, 2022). "Conditional deletion of NRP1 in macrophages compromised lipid uptake and led to insulin resistance." (PMID 36119080, 2022).
ischemic stroke (3 papers, 2023 to 2025). A stroke disorder caused by obstruction of blood flow to the brain, due to thrombotic (local blood clot formation) or embolic (due to a blood clot or other material traveling from another site) event. "Available literature documents that ischemic stroke can disrupt the morphology and function of mitochondria and that the latter in other disease models can be preserved by neuropilin-1 (NRP-1) via oxidative stress suppression." (PMID 37138283, 2023). "Finally, in accordance with other papers demonstrating that COVID‐19 patients had more severe ischemic strokes with worse outcomes, we found that S1rp increased oxygen glucose deprivation/reoxygenation‐induced toxicity in an additive manner, via the NRP1/HDAC4/CREB/RIPK1 pathway." (PMID 40746867, 2025). "NRP-1 can produce neuroprotective effects against I/R injury to the brain by activating the Wnt/β-catenin signaling pathway and promoting mitochondrial structural repair and functional recovery, which may serve as a promising candidate target in treating ischemic stroke." (PMID 37138283, 2023).
lung squamous cell carcinoma (3 papers, 2020 to 2022). "Moreover, NRP1 positively correlates with the oncogenic Cancer Associated Fibroblast (CAF), macrophage and endothelial cells infiltration, negatively correlates with infiltration of CD8+ T cell, the tumor killer cell in Lung Squamous cell carcinoma (LUSC)." (PMID 34168096, 2021).
Lymphadenopathy (3 papers, 2013 to 2022). Enlargement (swelling) of a lymph node. "Interestingly, disease in MRL.LPR is also associated with an increase in unusual CD4−CD8− T cells, a feature which leads to the severe lymphadenopathy in this model, but is not observed in human SLE; we observed that these cells were mostly PD‐1+, but only marginal NRP1 upregulation (Fig EV4G)." (PMID 36069030, 2022).
lymphopenia (3 papers, 2013 to 2025). Reduction in the number of lymphocytes. "Importantly, NRP1 expression remains stable on NRP1 positive or negative Treg subsets upon TCR mediated or lymphopenia induced cell activation and proliferation while environmental inflammatory stimuli have been shown to modulate NRP1 expression." (PMID 23908654, 2013).
malaria (3 papers, 2023 to 2025). Malaria is a serious and sometimes fatal disease caused by a parasite that commonly infects a certain type of mosquito which feeds on humans. "To investigate the role of Nrp-1 in CD8+ effector T cells during malaria, we first analyzed Nrp-1 expression on CD8+ T cells during PbA infection in C57BL/6 mice via flow cytometry." (PMID 38019895, 2023).
metastatic melanoma (3 papers, 2015 to 2021). A melanoma that has spread from its primary site to another anatomic site. "The results demonstrated that NRP1 expression was significantly increased in primary (56%) and metastatic melanoma (62%), compared with common nevi (11%) and dysplastic nevi (24%)." (PMID 25954957, 2015). "NRP1 staining was stronger in primary and metastatic melanoma biopsies than that in common nevi and dysplastic nevi cases." (PMID 25954957, 2015). "This indicated that increased NRP1 activity may be a common requirement for the transformation from benign neoplasia to malignancy, as well as for tumor progression from primary to metastatic melanoma." (PMID 25954957, 2015). "The results showed that NRP1 expression was also correlated with overall (HR, 1.65; 95% CI, 1.07–2.54; P=0.02), and disease specific 5-year survival (HR, 1.64; 95% CI, 1.06–2.53; P=0.03) in patients with metastatic melanoma." (PMID 25954957, 2015).
osteoarthritis (3 papers, 2021 to 2024). A noninflammatory degenerative joint disease occurring chiefly in older persons, characterized by degeneration of the articular cartilage, hypertrophy of bone at the margins and changes in the synovial membrane. "This study elucidated the role of SEMA3A in osteoarthritis and illustrated its action mechanism involving NRP-1." (PMID 34821196, 2021). "The mechanism responsible for osteoarthritis in patients treated with NGF mAbs is not understood, and whether NRP1 differentially regulates the pronociceptive and protective actions of NGF in joints is unknown." (PMID 39589827, 2024).
osteoporosis (3 papers, 2022). A condition of reduced bone mass, with decreased cortical thickness and a decrease in the number and size of the trabeculae of cancellous bone (but normal chemical composition), resulting in increased fracture incidence. "Collectively, we propose that miR-148a KO inhibits osteoclast formation and ameliorates bone loss by regulating the NRP1 signaling axis in an OVX-induced osteoporosis model." (PMID 36446758, 2022). "This study aimed to explore the associations of genetic variants in the semaphorin 3A (SEMA3A) signaling pathway genes, including SEMA3A, NRP1, PLXNA1, PLXNA2 and PLXNA3 with osteoporosis (OP) risk and bone mineral density (BMD) in a Chinese Han older adult population." (PMID 36425469, 2022).
periapical abscesses (3 papers, 2021 to 2023). "The results obtained indicated that ACE-2 and NRP-1 gene expression were significantly downregulated in periapical abscess, periapical granuloma, and radicular cyst when compared to healthy control (P ˂ 0.001)." (PMID 34749700, 2021).
periodontitis (3 papers, 2018 to 2022). An acute or chronic inflammatory process that affects the tissues that surround and support the teeth. "exFoxp3T cells in periodontitis-induced mice expressed regulatory T (Treg) cell signature molecules such as GITR, KLRG1, FR4, and Nrp1 to a similar extent to GFP+YFP+ T cells while GFP–YFP– T cells expressed these genes at a lower level." (PMID 29453398, 2018).
proliferative diabetic retinopathy (3 papers, 2021). Advanced retinopathy due to diabetes mellitus characterized by the formation of new vessels in the retina. "For example, patients suffering from late-stage proliferative diabetic retinopathy have elevated levels of vitreous Sema3A, which attracts neuropilin-1(NRP-1) positive mononuclear phagocytes." (PMID 34039431, 2021).
pulmonary hypertension (3 papers, 2020 to 2025). Increased pressure within the pulmonary circulation due to lung or heart disorder. "Moreover, NRP1 has been recently suggested as a potential biomarker to identify SSc patients who are at risk of developing pulmonary arterial hypertension." (PMID 35888144, 2022). "Our data demonstrate that COUP-TF2 drives NRP1 expression, facilitating lung vascular repair, although the body of literature suggests that COUP-TF2–mediated NRP1 signaling may promote pathologic angiogenesis in other lung disease contexts, possibly pulmonary hypertension or lung tumor angiogenesis." (PMID 33239293, 2020).
skin cancer (3 papers, 2015 to 2023). "Deletion of NRP1 in healthy epidermis prevents skin tumor initiation." (PMID 25954957, 2015). "We selected skin cancer-derived DJM-1 cells, which only express NRP1 as the VEGF-A receptor and grow faster than other cancer cells under anchorage-independent conditions." (PMID 26209534, 2015). "DJM-1, a human skin cancer cell line, expresses endogenous VEGF-A and NRP1." (PMID 26209534, 2015).
small cell lung carcinoma (3 papers, 2021 to 2023). Small cell lung cancer (SCLC) is a highly aggressive malignant neoplasm, accounting for 10-15% of lung cancer cases, characterized byrapid growth, and early metastasis. "SEMA3F binds to NRP1 to inhibit the small cell lung carcinoma cell colony formation." (PMID 37701532, 2023). "Using models of human small cell lung carcinoma, the investigators found that a higher proportion of CD8+ cells, rather than CD4+ cells, were expressing Nrp1, and that SEMA3a-NRP1 interactions inhibit CD8+ cell functions." (PMID 36203599, 2022).
thyroid cancer (3 papers, 2019 to 2024). "Moreover, it is interesting to note that the expression of NRP2, an important paralog of the NRP1 gene, has been correlated to lymph node metastasis of human PTC and is required in the VEGF-C/NRP2 mediated invasion and migration of thyroid cancer cells." (PMID 31614935, 2019).
Ureteral obstruction (3 papers, 2019 to 2026). Obstruction of the flow of urine through the ureter. "Furthermore, Nrp1 expression was higher in kidneys from mice with unilateral ureteral obstruction (UUO) and those with 5/6 nephrectomy than in their respective sham controls." (PMID 38977708, 2024). "In this study, we used a genetic approach to knockout Nrp1 specifically in kidney fibroblasts and analysed the impact of Nrp1 deletion in two well‐characterised models of CKD: unilateral ureteral obstruction (UUO) and folic acid (FA)‐induced nephrotoxicity." (PMID 41432227, 2026).
uveal melanoma (3 papers, 2021 to 2023). A melanoma derived from melanocytes of the uveal tract. "Interestingly, miR-205 regulates neuropilin-1 (Nrp1) expression in uveal melanoma and CRIPTO has been implicated in regulation of Nrp1 however, this connection remains tenuous." (PMID 34576327, 2021).
vascular malformation (3 papers, 2009 to 2022). A non-neoplastic disorder that is the result of defects of vascular morphogenesis. "This change in our understanding of the principal mechanisms regulating endothelial responses has wide implications for therapy, as Nrp1 inhibition becomes a highly attractive target to curb angiogenesis, or to modulate Tgf-β/Bmp responses in vascular malformations." (PMID 26081042, 2015). "Defects of developing blood vessels caused by Nrp1 gene knockdown in mice are different from vascular malformations displayed by mice lacking either SEMA3A or VEGF-A165 (Vegf-a120/120 mice)." (PMID 19175293, 2009).
acute pneumonia (2 papers, 2020 to 2022). "Pre-treatment with GLP significantly attenuated acute pneumonia by inhibiting inflammatory cell infiltration, reducing cytokine secretion, downregulating NRP1 expression and suppressing pneumonocyte apoptosis and autophagy." (PMID 36373992, 2022). "Overall, these results suggested that GLP inhibited apoptosis, promoted autophagy and suppressed the expression of NRP1 to relieve LPS-induced acute pneumonia." (PMID 36373992, 2022). "GLP could protect against LPS-induced acute pneumonia through multiple mechanisms: blocking the infiltration of inflammatory cells, inhibiting cytokine secretion, suppressing NRP1 activation and regulating pneumonocyte apoptosis and autophagy." (PMID 36373992, 2022). "Altogether, this study indicated that GLP could protect against LPS-induced acute pneumonia via diverse mechanisms, including the inhibition of inflammatory cell infiltration, reduction of cytokine secretion, downregulation of NRP1 expression and suppression of pneumonocyte apoptosis and autophagy." (PMID 36373992, 2022).
breast adenocarcinoma (2 papers, 2013 to 2025). "High expression of VEGF-related analytes in tumor cells, including VEGFR1 and neuropilin-1, is associated with worse overall survival in breast adenocarcinoma patients." (PMID 24244672, 2013).
cardiac ischemia (2 papers, 2019 to 2025). "Genes such as HES1 and NRP1 were important for progression of cardiac ischemia, but these genes may be linked with CAD." (PMID 31881747, 2019).
chronic kidney disease (2 papers, 2024 to 2026). Impairment of the renal function secondary to chronic kidney damage persisting for three or more months. "Collectively, these findings provide new insights into the signalling pathways controlling the transition from acute to chronic kidney disease conversion and identify NRP1 as a novel regulator of fibroblast supportive function." (PMID 41432227, 2026). "Here, the authors show that targeting of NRP1 represents a promising strategy for the treatment of kidney injury and subsequent chronic kidney disease." (PMID 38977708, 2024). "Together, these results reveal that targeting of NRP1 represents a promising strategy for the treatment of AKI and subsequent chronic kidney disease." (PMID 38977708, 2024). "Nrp1 interacts with both TGF-β and TNF-α receptors in distal TECs while activating the Nfkb1 and Smad3 pathway, regulating the secretion of collagen, suppressing OXPHOS, activating myofibroblasts, thereby accelerating the progression of acute and chronic kidney diseases." (PMID 38977708, 2024).
endometrial tumors (2 papers, 2016 to 2021). "Higher levels of NRP-1 expression in the endometrial tumors were associated with increasing levels of circulating HGF and G-CSF in matching patient serum (p = 0.0166 and 0.0148 respectively)." (PMID 26701889, 2016). "In conclusion, findings from this study suggest that aberrant NRP-1 expression may serve as an early biomarker for metastatic endometrial tumors, and potentially influence novel therapies to complement existing interventions." (PMID 26701889, 2016).
fetal growth restriction (2 papers, 2020 to 2021). A fetus that does not grow beyond the 10th percentile of conventionally accepted weight for gestational age. "Neuropilin-1 is expressed in decidual cells and syncytiotrophoblast, but it is reduced in placental samples from pregnancies complicated by pre-eclampsia and fetal growth restriction." (PMID 34149740, 2021).
glomerulosclerosis (2 papers, 2019 to 2022). A hardening of the kidney glomerulus caused by scarring of the blood vessels. "The transmembrane receptor neuropilin-1 (NRP-1) is highly expressed by mesangial cells and its genetic deletion results in proteinuric disease and glomerulosclerosis." (PMID 31533337, 2019).
irritable bowel syndrome (2 papers, 2011 to 2017). Irritable bowel syndrome (IBS) is a chronic functional condition of the lower gastrointestinal (GI) tract characterized by abdominal pain or discomfort and disordered bowel habit (diarrhea, constipation, or fluctuation between the two). "We noted that the spatial distribution and morphology if NRP-1 expressing cells resembles that of enteroendocrine cells (EEC) which are altered in response to disease state including cancer and irritable bowel syndrome (IBS)." (PMID 21401950, 2011).
latent infection (2 papers, 2013 to 2023). "As expected, phoP shows a high transcription rate in hypoxia (NRP1 and NRP2) and during the entire process of latent infection, this observation was in agreement with the increase of the pks genes transcription and the subsequent accumulation of polar precursors." (PMID 23472191, 2013).
liver cirrhosis (2 papers, 2020 to 2023). "Although this is, to our knowledge, the first time that NRP-1 has been studied in HCFs, it has been previously suggested that NRP-1 promotes liver cirrhosis progression and its aggravation." (PMID 32664340, 2020).
liver disease (2 papers, 2023 to 2024). "Concerning the liver, inhibition of NRP-1 has been shown to improve steatotic liver disease in obese mice." (PMID 38791476, 2024).